RETN (resistin)
Diseases named in the same sentence as RETN in open-access papers (continued):
Sharing a sentence is not in itself a finding about the gene and the disease.
steatosis (11 papers, 2012 to 2026). Increased lipid within the cytoplasm of cells. "RETN rs4804765 variant carriers showed less likelihood of obtaining the primary outcome (p = 0.03) and worse change in steatosis (p = 0.033), inflammation (p = 0.0078), ballooning (p = 0.034), and NAS (p = 0.0028)." (PMID 30065651, 2018). "In the regulation of adipose tissue, melatonin has been found to increase m6A RNA demethylation in adipocytes and inhibit resistin production, thereby improving steatosis." (PMID 39765828, 2024). "The positive correlation between resistin and IR, steatosis, and inflammation is well stablished in murine and cellular models, but data in human NAFLD are conflicting." (PMID 36009862, 2022). "SNPs associated with change in steatosis score were: ABCA1 rs2230806 (β = 0.35, p = 0.0087) and RETN rs4804765 (β = −0.32, p = 0.033)." (PMID 30065651, 2018). "The serum resistin in NASH patients is similar with that in the subjects with simple steatosis, while resistin content in NASH liver is significantly higher than that in the liver of simple steatosis." (PMID 24559185, 2014). "In parallel, NASH patients exhibited increased resistin protein expression detected by SQ-analysis than those in simple steatosis (3.12% ± 0.11% vs. 0.61% ± 0.09% per hpf, P < 0.05) and controls (vs. 0.30% ± 0.09% per hpf, P < 0.05)." (PMID 24559185, 2014). "Hepatic resistin mRNA expression was significantly up-regulated in NASH patients compared with simple steatosis group (P < 0.05) and controls (P < 0.05)." (PMID 24559185, 2014). "Furthermore, steatosis aggravation induced by resistin in mice is mediated by the AMPK/peroxisome proliferator-activated receptor gamma coactivator 1-alpha (PGC-1α) pathway." (PMID 36009862, 2022). "The probiotic mixture showed promise as a treatment for NAFLD pathogenesis, and may improve HFSD-induced steatosis through its effects on leptin, resistin, inflammatory biomarkers, and hepatic function markers." (PMID 28086768, 2017). "The present study was to evaluate the circulating and hepatic resistin expression in patients with biopsy-proven NASH and those with simple steatosis, and to assess the associations of resistin expression with metabolic profiles and inflammation in human liver." (PMID 24559185, 2014). "Similarly, resistin circulating levels did not associate with steatosis grade, NASH diagnosis, hepatic ballooning, or lobular inflammation grade, but they did correlate with fibrosis stage in obese NAFLD patients." (PMID 36009862, 2022). "Augmented hepatic resistin mRNA levels were reported in patients with NASH compared to steatosis or control subjects and in steatosis patients compared to control individuals." (PMID 36009862, 2022). "Interestingly, the immuno–histological assessment of hepatic samples of NAFLD patients revealed a resistin distribution predominantly in perisinusoidal cells (Kupffer cells and HSCs), histiocytes of inflammatory infiltrate, and histiocytes surrounding the hepatocytes with steatosis." (PMID 36009862, 2022). "Circulating resistin levels are increased in patients with NAFLD and NASH, and circulating resistin levels in patients with NAFLD are related to the severity of steatosis, inflammation, and fibrosis." (PMID 33925827, 2021). "Hepatic resistin was significantly increased in NASH patients in both mRNA and protein levels than those in simple steatosis and control subjects (all P < 0.05)." (PMID 24559185, 2014). "In contrast, a study described a negative correlation between circulating resistin levels and the steatosis grade in severely obese NAFLD patients." (PMID 36009862, 2022). "Serum resistin level in NAFLD patients had a positive correlation with WHR (r = 0.41, P = 0.001), ALT (r = 0.31, P = 0.02), GGT (r = 0.35, P = 0.007), TG (r = 0.34, P = 0.01), CK-18 fragment level (r = 0.64, P = 0.02) and histological grade of steatosis (rho = 0.43, P = 0.001)." (PMID 24559185, 2014).
steatosis (continued). "These SQ-analysis results of resistin protein expression were in agreement with the western blotting results from a small proportion of patients with co-existence of both NASH and gallstone, patients with concomitant simple steatosis and gallstone, and controls." (PMID 24559185, 2014).
type 1 diabetes mellitus (11 papers, 2013 to 2025). A chronic condition characterized by minimal or absent production of insulin by the pancreas. "We also found that down-regulated pathways affected by RETN include allograft rejection, graft versus host disease, ribosome, spliceosome, type I diabetes mellitus." (PMID 40599778, 2025). "Higher resistin levels were also observed in a group of children and adolescents with type 1 diabetes compared to healthy controls, supporting that resistin is associated with insulin metabolism discrepancies." (PMID 36360347, 2022). "CD163, MCEMP1 and RETN may jointly regulate complement and coagulation cascades, toll like receptor signaling pathway, graft versus host disease, type I diabetes mellitus." (PMID 40599778, 2025). "Using machine learning models to predict the potential mechanisms and targets of CD163, MCEMP1, and RETN proteins, CD163, MCEMP1 and RETN may jointly regulate complement and coagulation cascades, toll like receptor signaling pathway, graft versus host disease, type I diabetes mellitus." (PMID 40599778, 2025).
autoimmune disease (10 papers, 2013 to 2025). A disorder resulting from loss of function or tissue destruction of an organ or multiple organs, arising from humoral or cellular immune responses of the individual to their own tissue constituents. "In humans, resistin is mainly released by peripheral blood mononuclear cells (PBMCs), macrophages and bone marrow cells and is under study for involvement in various metabolic, inflammatory and autoimmune diseases." (PMID 33142854, 2020). "In addition, adipocytes secrete various cytokines, such as leptin, adiponectin, IL-6, resistin, visfatin and TNF-α, which regulate the proliferation and differentiation of T cells and are involved in many chronic inflammatory and autoimmune diseases." (PMID 33329579, 2020).
endometrial cancer (10 papers, 2015 to 2025). Primary or metastatic malignant neoplasm involving the endometrium (mucous membrane that lines the endometrial cavity). "Pro-inflammatory adipokines such as leptin, visfatin, and resistin are also implicated in the progression and spread of endometrial cancer cells." (PMID 39941769, 2025). "The latest available studies show that elevated resistin levels correlate with endometrial cancer stimulation, development and invasion, which is associated with advanced cancer stage and a worse prognosis for the patient." (PMID 37190027, 2023). "SNPs, particularly the polymorphisms of the resistin gene 420 G > C and the 62 G > A gene, are believed to play an important role in the development of endometrial cancer." (PMID 37190027, 2023). "On review of the literature, adiponectin, leptin, resistin and visfatin are found to be most commonly studied in the context of endometrial cancer risk and progression." (PMID 34951691, 2022). "Recent studies have demonstrated that circulating resistin levels are significantly elevated in patients with breast, gastric, colorectal, lung and endometrial cancers, suggesting that serum resistin can be a potential diagnostic biomarker for cancers." (PMID 36497484, 2022). "However, some reports linked resistin to some types of gender-related cancer, which mainly occur in women, e.g., breast cancer and endometrial cancer." (PMID 35453670, 2022). "Leptin, visfatin and resistin are linked to the stimulation of endometrial cancer growth, proliferation, invasion and metastasis and are associated with worse prognosis or with a higher grade/stage of endometrial cancer." (PMID 34951691, 2022). "Pro-inflammatory adipocytokines, including leptin, visfatin, and resistin, play a role in the progression of endometrial cancer." (PMID 38201606, 2023). "The pro-inflammatory adipocytokines leptin, visfatin, and resistin are also involved in the progression and spread of endometrial cancer cells." (PMID 38201606, 2023). "Several studies have shown a higher resistin level in some cancer types, including esophageal squamous cancer, malignant lymphoma, gastric, colorectal, breast, and endometrial cancer." (PMID 35453670, 2022). "Increasing serum resistin levels correlate with the progression of breast, colon and endometrial cancers." (PMID 31719210, 2019). "Serum levels of resistin are known to increase in breast, colon, and endometrial cancer during tumor progression, although few studies have investigated the role of resistin in bone cancers, especially in osteosarcoma." (PMID 31719210, 2019). "This group revealed that the endometrial cancer patients have significantly higher levels of circulating resistin, relative to the control subjects." (PMID 30131543, 2018). "In addition, resistin may play a role in breast and endometrial cancer." (PMID 26425347, 2015). "Based on these results, we could hypothesize that the decreased resistin level in BBD may be a biochemical marker of metabolic alterations related to the development of BC and other neoplasms such as epithelial ovarian cancer, endometrial cancer, and esophageal squamous cell carcinoma." (PMID 35627631, 2022).
hyperthyroidism (10 papers, 2012 to 2025). Overactivity of the thyroid gland resulting in overproduction of thyroid hormone and increased metabolic rate. "Two studies by the same author reported an association between hyperthyroidism (2005) and hypothyroidism (2006) and circulating resistin levels." (PMID 36686437, 2022). "This meta-analysis confirms that resistin is significantly associated with an increased risk of hyperthyroidism and subclinical hypothyroidism, but it has only a small effect on hypothyroidism." (PMID 36686437, 2022). "Additionally, the successful treatment of hyperthyroidism is associated with decreased resistin levels." (PMID 40563510, 2025). "As demonstrated in the literature, serum resistin concentrations were found to be higher in hyperthyroidism patients than in hypothyroidism patients (6.378 vs. 5.81 ng/mL, respectively)." (PMID 40563510, 2025). "The authors showed higher adiponectin and lower resistin levels in hyperthyroidism than in hypothyroidism." (PMID 35399935, 2022). "The resistin levels of patients with hyperthyroidism after treatment were significantly lower than those before treatment (MD = 2.16, 95% CI = 1.00–3.32, P < 0.05, I2 = 93%, Pheterogeneity = 0.0003)." (PMID 36686437, 2022). "Recently, researchers demonstrate that apart from abnormal circulating levels of TH and thyroid-stimulating hormone (TSH), changes in profile of adipokines (like adiponectin, leptin and resistin, etc.)also have been found in patients with hyperthyroidism." (PMID 30670019, 2019). "The first such report found that patients with hyperthyroidism had less serum resistin level than euthyroidism controls and its concentration was not modified after attainment of euthyroidism." (PMID 27637079, 2016). "There were also several studies demonstrating that resistin is up-regulated in hyperthyroidism patients and returned to normal range after normalizing thyroid hormones." (PMID 27637079, 2016). "Patients with hyperthyroidism showed a decrease in serum resistin level compared with healthy control subjects (8.63 ± 4.41 vs. 11.69 ± 6.44 pg/ml; p=0.03)." (PMID 27637079, 2016). "In our study, higher serum levels of resistin in patients with hypothyroidism and hyperthyroidism were observed." (PMID 27193069, 2016). "Higher resistin levels in both hypothyroidism and hyperthyroidism were observed compared to controls." (PMID 23533949, 2013). "The significant diminution of serum resistin in the OT group corroborates the first study performed on humans, in which patients with hyperthyroidism exhibited low serum resistin concentrations." (PMID 22645452, 2012). "The blood levels of metabolic hormones, including adipokines (insulin, adiponectin, leptin, apelin, chemerin, resistin, visfatin, vaspin, and omentin), in patients with thyroid dysfunction (hyperthyroidism and hypothyroidism) and correlations between thyroid and metabolic hormones." (PMID 40563510, 2025). "The resistin levels of patients with thyroid dysfunction after treatment were significantly lower than those before treatment (MD = 1.00, 95% CI = 0.34–1.65, P = 0.003), especially in patients with hyperthyroidism (MD = 2.16, 95% CI = 1.00–3.32, P = 0.0003)." (PMID 36686437, 2022). "Furthermore, the resistin levels of patients with hyperthyroidism (MD = 3.23, 95% CI = 0.68–5.79, P = 0.01) and subclinical hypoidism (MD = 1.37, 95% CI = 0.31–2.42, P = 0.01) were significantly higher than those of euthyroid controls." (PMID 36686437, 2022). "Therefore, in the present study, we evaluated serum levels of adiponectin, resistin and leptin, as well as cholesterol and triglycerides in patients with newly diagnosed patients with hypothyroidism and hyperthyroidism." (PMID 27193069, 2016). "However, these initial findings contrast with subsequent studies that report high resistin levels in hyperthyroidism patients, showing a divergence in the data." (PMID 22645452, 2012).
hyperthyroidism (continued). "Nevertheless, resistin gene expression is almost undetectable in rats with hyperthyroidism." (PMID 22645452, 2012). "However, resistin levels were severely low in mice with hyperthyroidism." (PMID 36686437, 2022). "As refered before, there is striking evidence that TH excess lead to prominent changes in classical adipokines (like adiponectin, leptin and resistin, etc.), we wonder serum ZAG, a novel lipid-mobilizing adipokine, whether changed in hyperthyroidism patients." (PMID 30670019, 2019).
lymph node metastasis (10 papers, 2015 to 2025). "They found that resistin expression was significantly associated with increased tumor size, clinical stage and lymph node metastasis, and negatively associated with PFS and OS." (PMID 36624406, 2023). "High resistin levels in NPC patients were positively associated with lymph node metastasis, and resistin promoted the migration and invasion of NPC cells in vitro." (PMID 36497484, 2022). "The study further investigated the correlation between resistin expression and various clinicopathological variables, including age, sex, smoking status, comorbid conditions, clinical stage, differentiation, lymph node metastasis, and total metastasis." (PMID 40002704, 2025). "Here, we found that high serum resistin levels in NPC patients were positively correlated with lymph node metastasis and that resistin promoted the metastasis of NPC cells both in vitro and in vivo." (PMID 36497484, 2022). "In conclusion, the findings of this study demonstrate that serum resistin levels are positively correlated with the risk of NPC development and can potentially serve as an independent predictor of lymph node metastasis in NPC cases." (PMID 36497484, 2022). "Cox multivariate analysis showed that resistin expression was an independent factor for determining disease-free survival, whereas lymph node metastasis, resistin expression, and age (≥55 years) were independent factors affecting overall survival." (PMID 34659568, 2021). "Strongly positive resistin expression is significantly associated with a number of clinical parameters in CRC patients, including tumor stage and lymph node metastasis." (PMID 32420377, 2020). "We also observed significant associations between a strongly positive level of resistin expression and clinical parameters in CRC tissue specimens, including tumor stage (P = 0.022) and lymph node metastasis (P = 0.009)." (PMID 32420377, 2020). "Notably, a significantly positive correlation was observed between resistin expression in lung adenocarcinoma tissues and both other metastasis (excluding lymph node metastasis) (p < 0.01) and overall metastasis (p < 0.01)." (PMID 40002704, 2025). "Importantly, we showed that the serum resistin levels were positively correlated with lymph node metastases in NPC patients." (PMID 36497484, 2022). "Moreover, the serum resistin level was a significant independent predictor for lymph node metastasis in NPC patients, according to multivariate logistic regression analysis after adjusting for established or suspected risk factors of NPC, including age, gender, EBV VCA-IgA and EBNA1 IgA." (PMID 36497484, 2022). "We demonstrated that leptin, resistin, and visfatin might increase the risk of onset and lymph node metastasis of postmenopausal BC cases only and not in premenopausal BC group." (PMID 25838618, 2015). "Resistin (RETN) is a cysteine-rich adipose-derived peptide hormone involved in inflammatory processes that have shown a correlation with late-stage OSCC and lymph node metastasis." (PMID 39769275, 2024). "A positive correlation between higher levels of resistin expression and the degree of histological differentiation of EOC and the incidence of lymph node metastasis has also been shown." (PMID 37238197, 2023). "Through analyzing the differences in serum resistin levels with clinical characteristics, we observed different levels of serum resistin in NPC patients with different types of lymph node metastasis." (PMID 36497484, 2022).